CRP (C-reactive protein)
Diseases named in the same sentence as CRP in open-access papers (continued):
Sharing a sentence is not in itself a finding about the gene and the disease.
anemia (continued). "Occult malnutrition was defined by the coexistence of at least two abnormal biological markers: hypoalbuminemia (albumin < 3.5 g/dL), anemia (Hb < 12 g/dL), and elevated CRP (>0.5 mg/dL)." (PMID 41754103, 2026). "The most common features are elevation of acute phase reactants ESR, CRP, and thrombocytosis and a chronic, hypochromic anaemia." (PMID 41466885, 2026). "Laboratory studies showed anemia (hemoglobin 10.6 g/dL), markedly elevated CRP (181.9 mg/L) and erythrocyte sedimentation rate (47 mm/hr), and a normal leukocyte count." (PMID 41952923, 2026). "Laboratory findings of anemia, low hematocrit levels, neutrophilic leukocytosis, and increased amylases, lipases, CRP, and procalcitonin levels have been reported." (PMID 40731941, 2025). "Severe hypochromic/microcytic anemia was detected, along with leucopenia, moderate hypoalbuminemia, and mildly elevated C-reactive protein." (PMID 40046384, 2025). "Labs at presentation demonstrated a normal leukocyte count, mild anemia, and mild elevation of C-reactive protein (CRP)." (PMID 40895920, 2025). "Initial laboratory evaluation demonstrated profound anemia (hemoglobin: 4.8 g/dL), elevated inflammatory markers (C-reactive protein (CRP): 26.9 mg/L), and impaired renal function (creatinine: 2.76 mg/dL)." (PMID 40823461, 2025). "Serial laboratory investigations revealed leukopenia with severe neutropenia (WBC: 2.1 × 109/L, absolute neutrophil count <0.5 × 109/L), markedly elevated CRP (94.6 mg/L), and critical anemia (HGB: 51 g/L)." (PMID 41278037, 2025). "Laboratory investigations revealed anemia, elevated CRP, and ESR, with a CD4 count of 441 cells/mcL." (PMID 40024178, 2025). "Laboratory data on admission showing mild anemia, mildly elevated CRP, and marked elevations in D-dimer and CYFRA 21-1, with other parameters mostly within normal limits." (PMID 41426883, 2025). "Studies on the relationship between anemia and the C-reactive protein–albumin–lymphocyte (CALLY) index, a novel inflammatory measure, are scarce." (PMID 41204576, 2025). "Elevated CRP levels (p = 0.007) and a higher incidence of anemia (p = 0.049) were observed in the high NLR group." (PMID 41333516, 2025). "Her blood test results showed low iron levels, high ferritin levels, and markedly elevated C-reactive protein (CRP) levels, suggesting that anemia was likely caused by chronic inflammation." (PMID 40589696, 2025). "Uniform presentations included oral aphthosis (100%), intestinal lesions (100%), with most cases exhibiting fever (85.7%), anemia (85.7%), and elevated C-reactive protein (CRP) levels (85.7%)." (PMID 40616106, 2025). "Screening for anemia should include at least a complete blood count, C-reactive protein, and ferritin levels." (PMID 41244250, 2025). "Laboratory tests showed progressive anemia (hemoglobin 94 g/L), thrombocytopenia (platelet count 52 × 109/L), and elevated C-reactive protein (11.9 mg/L)." (PMID 41305810, 2025). "The combined decrease in hemoglobin levels and elevated ALT and CRP indicate mild anemia with hepatic involvement." (PMID 41156578, 2025). "At the time of admission, blood tests showed elevated white blood cells (WBC, 10.70 × 10∧9/L), with a neutrophil percentage of 76.0%, moderate anemia (hemoglobin 84 g/L), and a significantly elevated C-reactive protein (CRP) level (75.73 mg/L)." (PMID 40950993, 2025). "It defines anemia using Hb thresholds and identifies SF as the primary marker of iron status, with adjustments for inflammation using markers such as C-reactive protein (CRP) and alpha-1-acid glycoprotein." (PMID 40872496, 2025). "Hemoglobin (Hb) concentration (anemia index) and serum C-reactive protein (CRP) levels in the probiotic group and placebo group before and after intervention." (PMID 40735439, 2025).
anemia (continued). "Persistent fever, muscle weakness, loss of appetite and night sweats and anemia, polyclonal gammopathy, elevated urea and creatinine, increased ESR and CRP protein levels, and a high proportion of plasma cells (40%) observed in bone marrow puncture." (PMID 41357194, 2025). "Our approach achieves clinically meaningful stratification using a model with five variables (age, anemia, CRP, ASA score, and surgical delay), substantially fewer than high-dimensional machine learning models in the literature, which feature 60+ variables." (PMID 41302186, 2025). "Among those women with anemia at 36 weeks’ gestation, the prevalence of concurrent inflammation (elevated (CRP)) was 33/100 (33.0%) in the FCM group compared to 35/136 (25.7%) in the SOC group." (PMID 39762420, 2025). "RVGE infants exhibit pronounced abnormalities, including elevated white blood cell counts, anemia, and elevated C-reactive protein (CRP), reflecting a state of systemic inflammation." (PMID 41472213, 2025). "They exhibited characteristic cytopenias (neutropenia, lymphocytopenia, anemia, and thrombocytopenia) alongside elevated inflammatory markers (CRP, LDH, ferritin, D-dimer) and hypoalbuminemia, consistent with established HV features." (PMID 41487580, 2025). "Lymphopenia, neutrophilia, anemia, and thrombocytopenia, as well as significantly high inflammatory markers (CRP, ESR) and liver transaminases, elevations in cardiac biomarkers, such as troponin, BNP, and pro-BNP, are frequently reported." (PMID 41135595, 2025). "A 79-year-old male patient on hemodialysis for 29 years was admitted to the hospital with unexplained fever (C-reactive protein, 16.1 mg/dL), anemia (hemoglobin 7.6 g/dL), and multiple joint swelling that began 7 months earlier." (PMID 40571902, 2025). "Initial bloodwork revealed very mild normocytic anemia (hemoglobin, 122 g/L) but significantly elevated CRP (190 mg/L)." (PMID 40295291, 2025). "After 6 and 12 weeks of induction therapy, there was an improvement in anemia and thrombocytopenia, normalization of albumin levels, decrease in C-reactive protein (CRP) to normal levels, improvement in hepatosplenomegaly, and a reduction in bone lesions." (PMID 41142607, 2025). "Before the fourth dose, anemia persisted (Hb: 8.2 g/dL) with monocytosis, eosinophilia, and increased CRP (18.2 mg/L)." (PMID 41011540, 2025). "Suspecting vasculitis, the patient was started on prednisolone 1 mg/kg, which normalised ESR, CRP and other acute-phase markers and corrected the anaemia." (PMID 40922821, 2025). "Mediation of anaemia by CRP and BMI exhibited true suppression (ACME > 0; ADE < 0), precluding valid proportion‐mediated estimates and reinforcing our focus on separate indirect and direct effects." (PMID 40968580, 2025). "Reported changes include lymphopenia, neutrophilia, anemia, thrombocytopenia, elevated CRP, ESR, liver enzymes, and cardiac biomarkers." (PMID 41561503, 2025). "As compared to controls, COVID patients presented mainly with anemia and enhanced inflammatory markers, including increased C-reactive protein (CRP) and neutrophil-to-lymphocyte ratio (NLR) and decreased leucocyte-to-lymphocyte ratio (LLR)." (PMID 41226417, 2025). "On day four of antibiotic administration, levels of inflammation markers peaked (C-reactive protein: 208.7 mg/L) and the patient experienced transient anemia and thrombocytopenia (hemoglobin: 81 g/L; platelets: 79× 109/L) requiring transfusion." (PMID 40062160, 2025). "At the initial evaluation around age 3.5 years, the patient exhibited anemia, reactive thrombocytosis, and markedly elevated C-reactive protein (CRP), consistent with active systemic inflammation." (PMID 41465118, 2025). "It is well known that inflammatory indicators of IBD for disease activation in laboratory parameters are anaemia, thrombocytosis, hypoalbuminemia, elevated CRP, and ESR." (PMID 40283634, 2025).
anemia (continued). "The occurrence of anemia was closely related to female gender, underweight, ossification, and abnormal CRP and ESR." (PMID 39908327, 2025). "Laboratory evaluation revealed mild anemia (Hb: 10.4 g/dL) and elevated C-reactive protein (CRP: 25.6 mg/L), while the white blood cell count remained within normal limits, suggesting chronic inflammation rather than an acute infectious process." (PMID 40308392, 2025). "These include anemia, hypoalbuminemia, and elevated inflammatory markers such as C-reactive protein (CRP) and interleukin-6 (IL-6)." (PMID 39861412, 2025). "In multivariate analysis, malnutrition (adjusted OR: 2.41; 95% CI: 1.82–3.22), low BMI, anemia, elevated CRP, advanced FIGO stage, open surgery, preoperative lymphopenia, and older age were independently associated with poor immune recovery." (PMID 41169363, 2025). "Inflammatory cytokines are the main contributors to RA pathophysiology that produce systemic effects such as acute-phase protein (CRP) formation, anemia, cardiovascular disorders, and osteoporosis." (PMID 40575729, 2025). "Initial laboratory investigations revealed anemia with a hemoglobin level of 92 g/L, while white blood cell count, platelet count, and C-reactive protein levels were within normal ranges." (PMID 40830970, 2025). "Laboratory tests showed mild anemia and thrombocytopenia, elevated C-reactive protein suggesting systemic inflammation, mild liver enzyme elevation, and moderate renal impairment, while other results were normal." (PMID 41409952, 2025). "Laboratory findings revealed that all patients exhibited anemia and thrombocytopenia, and leukopenia was observed in four patients, and CRP levels were elevated in all cases." (PMID 40423365, 2025). "Patients with diagnoses of both HT and anemia stood out with higher discharge CRP levels compared to those with other metabolic conditions or comorbidities." (PMID 40282996, 2025). "Features indicating a chronic inflammatory state such as raised CRP, hypoalbuminaemia and anaemia were more common in this group (all P < 0.01)." (PMID 38548670, 2025). "Admission labs revealed normocytic anemia (hemoglobin 10.4 g/dL, hematocrit 32.2 %), elevated C-reactive protein (CRP) (4.6mg/dL), and metabolic acidosis." (PMID 40893459, 2025). "The case involves a 4.5-month-old puppy adopted from southern Italy with papulo-nodular skin lesions and generalized lymphadenomegaly as well as a mild normocytic normochromic anemia and increased C-reactive protein." (PMID 40711313, 2025). "Our patient had multicentric lymphadenopathy with defined histopathology, presented with 6 out of 11 minor criteria: elevated CRP, anemia, hypoalbuminemia, polyclonal hypergammaglobulinemia, constitutional symptoms, and splenomegaly." (PMID 40283629, 2025). "Laboratory data revealed leukopenia, mild anemia, hypoalbuminemia, elevated C-reactive protein, and mild elevation of SP-A, while most infectious and autoimmune serologies were negative." (PMID 41399553, 2025). "MWU analysis of EHR features highlighted preoperative measures of anemia (hemoglobin: p-value = 1.19E-05; erythrocytes: p = 1.00E-05) and infection parameters (CRP: p = 3.19E-05)." (PMID 41454043, 2025). "The multifactorial analysis conducted in this study revealed that gender, BMI, ectopic ossification, CRP, and ESR are independent risk factors influencing anemia in AS." (PMID 39908327, 2025). "In summary, CRP, albumin, and lymphocytes are important and interrelated elements in the occurrence and development of anemia." (PMID 41204576, 2025). "Laboratory results obtained at follow-up (9 July 2025), showing persistent microcytic anaemia, normal inflammatory biomarkers (hs-CRP and interleukin-6), stable renal function, and lipid profile within acceptable limits for age." (PMID 41362385, 2025). "Laboratory tests on admission showed mild anemia and thrombocytopenia, with markedly elevated CRP levels indicating systemic inflammation." (PMID 41409952, 2025).
anemia (continued). "Laboratory investigations revealed azotemia, anemia, markedly elevated amylase and lipase, and elevated C-reactive protein (CRP)." (PMID 41163640, 2025). "When comparing anemia subtypes, increased CRP levels tended to be more common in the normochromic-normocytic than in the hypochromic-microcytic or hyperchromic-macrocytic patients, without reaching statistical significance." (PMID 40636681, 2025). "The results display normocytic/normochromic anemia, leucopenia with lymphopenia, hepatic cytolysis, and elevated C-reactive protein." (PMID 40062099, 2025). "The most common clinicopathologic findings were increased CRP (87.4%), thrombocytopenia (85.1%), anemia (78.7%), hyperbilirubinemia (74.2%), decreased iron levels (51.1%), and leukopenia (49.7%)." (PMID 40817086, 2025). "Blood tests displayed hypochromic/microcytic anemia, hypoalbuminemia, and mildly elevated C-reactive protein." (PMID 40046384, 2025). "Laboratory studies revealed abnormalities: most notably, persistent elevation of inflammatory markers (C-reactive protein and erythrocyte sedimentation rate) accompanied by cytopenias ranging from isolated anemia to pancytopenia." (PMID 40247386, 2025). "Laboratory workup revealed mild anemia and raised CRP, but normal white cell count and organ function." (PMID 41035577, 2025). "Blood tests revealed mild anemia, renal impairment, and slightly elevated C-reactive protein (CRP) levels." (PMID 40264614, 2025). "Investigations showed normocytic anemia with a hemoglobin level of 96 g/L and an elevated CRP level at 55 mg/L." (PMID 40295291, 2025). "Anaemia odds rose with log‐CRP in a near‐linear fashion up to CRP levels of 50 mg/L, reflecting inflammation's role in anaemia of chronic disease." (PMID 40968580, 2025). "Blood tests revealed neutrophilic leukocytosis, microcytic, hypochromic anemia, and increased C-reactive protein (CRP) of 225.4 mg/L." (PMID 40843885, 2025). "Anemia was noticed in 18.7% of cases, lymphopenia in 8.7%, thrombocytopenia in 8.0%, and elevated CRP levels in 33.1% of cases." (PMID 40225278, 2025). "The frequency was 70.2% for elevated white blood cells, 73.0% for elevated c-reactive protein, 37.9% for anemia, 43.1% for genital lesions, 7.0% for pregnancy and 2.6% for HIV." (PMID 40552167, 2025). "Laboratory investigations revealed mild anaemia (haemoglobin, or Hb 95 g/L) and elevated C-reactive protein (CRP) (49 mg/L), while other parameters were normal." (PMID 41439055, 2025). "Regarding inflammatory syndrome in our patients, we analyzed the CRP and fecal calprotectin levels, as well as the grade of anemia." (PMID 41226329, 2025). "Their laboratory findings were notable for anemia, metabolic acidosis, hypoalbuminemia, elevated serum pro-B type natriuretic peptide (proBNP), cardiac enzymes, C-reactive protein (CRP), and procalcitonin level." (PMID 40290138, 2025). "Laboratory exams revealed worsening leukopenia (WBC 2.48 × 103 uL), anemia (hemoglobin 8.1 g/dL), thrombocytopenia (PLTs 30 000/mm3), hyponatremia (Na 130 mEq/L), and elevated ferritin (706 ng/mm3), C‐reactive protein (CRP) was 97 mg/L." (PMID 39731652, 2025). "Initial labs demonstrated anemia (Hb 94 g/L), hypoalbuminemia (25-30 g/L), markedly raised C-reactive Protein (CRP) (91-110 mg/L), and elevated angiotensin-converting enzyme (ACE) (92 U/L), suggesting systemic inflammation and possible granulomatous disease." (PMID 41450390, 2025). "Malnutrition was a strong predictor (adjusted OR: 2.41; 95% CI: 1.82–3.22; P < 0.001), along with BMI <18.5 kg/m2, anemia, elevated preoperative CRP, advanced FIGO stage, ovarian cancer, open surgery, preoperative lymphopenia, and age ≥60 years (all P < 0.05)." (PMID 41169363, 2025). "Compared with controls, pneumonia patients showed more frequent inflammation and organ injury markers (elevated C-reactive protein, procalcitonin, D-dimer, creatinine, and anemia)." (PMID 41356465, 2025).
anemia (continued). "Laboratory tests revealed severe anemia (hemoglobin, 78 g/L), hypoalbuminemia (14 g/L), and markedly elevated high-sensitivity C-reactive protein (144 mg/L)." (PMID 41465955, 2025). "Laboratory tests revealed elevated C-reactive protein (CRP), creatine kinase (CK), anemia, leukopenia, thrombocytopenia, and decreased complement levels." (PMID 40125233, 2025). "Laboratory findings revealed worsening anemia, elevated liver enzymes, and markedly increased C-reactive protein (CRP) levels, consistent with a systemic inflammatory response." (PMID 41002576, 2025). "KICS is a newly described condition that typically manifests with fever, anemia, thrombocytopenia, hypoalbuminemia, hyponatremia, hepatosplenomegaly, elevated CRP, and increased IL‐6 and IL‐10 levels, along with a high HHV‐8 viral load." (PMID 41424756, 2025). "The prevailing grade 1–2 side effect was anemia in 76.7% of the patients, while 61.8% exhibited elevated CRP, 54.2% developed lymphocytopenia, and 48.1% displayed pathologically elevated LDH." (PMID 38877146, 2024). "The patient’s gradual exacerbation of pain, particularly in the spine and pelvis, coupled with new-onset anemia and elevated CRP levels, warranted further investigation beyond the scope of FM." (PMID 39070404, 2024). "Increased ESR, increased total white blood cell count, normocytic normochromic anemia, neutrophilia, thrombocytosis, and CRP are usually noted in the literature for RDD patients." (PMID 38989342, 2024). "All women with ED suffered from anaemia based on their haemoglobin levels as well as dyslipidemia, hypoalbuminaemia, and high C-reactive protein levels." (PMID 38867850, 2024). "Both cases required comprehensive evaluations, revealing anemia, thrombocytopenia, elevated leukocyte count, and high C-reactive protein (CRP) levels." (PMID 39791064, 2024). "Another study through clinical pathological changes in co-infection of tick-borne pathogens in dogs identified anemia, thrombocytopenia, hypoalbuminemia, increased β2 and γ globulin fractions, and an increase in C-reactive protein concentrations." (PMID 38628944, 2024). "Patients with a higher NAC disease stage at diagnosis had a higher prevalence of anemia, hyponatremia, high urea, deranged liver function test results, and an elevated CRP and troponin‐T." (PMID 38314569, 2024). "He had moderate anemia (Hb=9.5 g/dl), raised acute phase reactants (CRP-47mg/L, ESR-79mm/hr) normal platelets (352 x109/L), normal INR (1.18) and a raised urine protein to creatinine ratio (Pr:Cr=0.23 g/mmol)." (PMID 38760753, 2024). "Laboratory work-up showed ESR was elevated in 15 (38%) patients, C reactive protein (CRP) was elevated in 26 (65%) patients and anemia was present in 7 (18%) patients." (PMID 39731440, 2024). "Patients with a higher NYHA class at diagnosis had a higher prevalence of anemia, high urea, deranged liver function test results, and elevated CRP and troponin‐T." (PMID 38314569, 2024). "Clinical manifestations of RDD often include painless lymphadenopathy, fever, anemia, leukocytosis, elevated C-reactive protein, accelerated erythrocyte sedimentation rate, and hypergammaglobulinemia." (PMID 38903706, 2024). "She presented with fever, polyserositis, hematochezia, and vomiting, and her blood tests indicated anemia (hemoglobin 5.6 g/dL), hypoalbuminemia (2.3 g/dL), coagulopathy, and elevated CRP (4.59 mg/dL)." (PMID 39339784, 2024). "While alpha-fetoprotein (AFP) and C-reactive protein (CRP) are amongst the most studied ones, the prognostic role of anaemia, a condition often found in cancer patients, is less clear." (PMID 38848660, 2024). "A 28-year-old female presented with symptoms of diarrhea, abdominal pain, asthenia, and inappetence, accompanied by abdominal collateral circulation, anemia, alteration of liver enzymes, and elevation of C-reactive protein levels." (PMID 39093785, 2024).